TNFSF11 (TNF superfamily member 11)
Diseases named in the same sentence as TNFSF11 in open-access papers (continued):
Sharing a sentence is not in itself a finding about the gene and the disease.
lung carcinoma (33 papers, 2013 to 2025). "A further example comes from the lung cancer data set where the gene TNFSF11 showed the highest loss of connectivity." (PMID 24489837, 2014). "As precision medicine comes to the forefront, stratifying lung cancer patients based on TNFSF11 expression becomes instrumental in tailoring therapeutic interventions." (PMID 38594779, 2024). "Recent studies indicated that both strands of miR-4732-5p and miR-4732-3p prevented lung cancer aggressiveness through inhibited TBX15/TNFSF11 axis or PI3K/Akt/GSK3β/Snail pathway." (PMID 39337462, 2024). "Most importantly, we proposed the use of ferroptosis inhibitors to specifically target cells with high TNFSF11 expression as a treatment method for lung cancer." (PMID 38594779, 2024). "The TNFSF11/TNFRSF11A pathway regulates the activation of osteoclasts and induces the migration of tumor cells, notably in breast and lung cancer." (PMID 34504794, 2021). "In conclusion, our study demonstrated the adverse prognostic role of TNFSF11 in lung cancer, and also discovered a negative correlation between TNFSF11 and GPX4." (PMID 38594779, 2024).
breast tumor (31 papers, 2006 to 2024). "Contrary to previous studies, the expression of TNFSF11/RANKL was consistently downregulated in patients aged ≤40 years with breast tumors as compared with adjacent normal breast tissues." (PMID 35741056, 2022). "In addition, the expression of TNFSF11/RANKL—which was found to be downregulated in breast tumors of patients aged ≤40 years—was upregulated in normal breast tissues, similar to the upregulation in another dataset of normal breast tissues." (PMID 35741056, 2022).
autoimmune disease (27 papers, 2005 to 2025). A disorder resulting from loss of function or tissue destruction of an organ or multiple organs, arising from humoral or cellular immune responses of the individual to their own tissue constituents. "Finally, we examined cis-pQTLs of the HLA-pGenes identified from the flagship pQTL study, and found that the cis-pQTLs of five HLA-pGenes—CD5, CD6, IL7R, SLAMF8, and TNFSF11—are themselves associated with autoimmune diseases with HLA risk." (PMID 39085222, 2024).
psoriasis (21 papers, 2012 to 2025). An autoimmune condition characterized by red, well-delineated plaques with silvery scales that are usually on the extensor surfaces and scalp. "TNFSF11, which was reported to be more highly expressed in one psoriasis lesion, was not significantly differentially expressed on the transcript level in our sample sets or in the published data." (PMID 23308107, 2013). "Other cytokines and receptors with low expression levels and consistently minimal or no changes in psoriasis (IL13, TNFRSF11A, TNFRSF11B, and TNFSF11) showed similar results across all three platforms." (PMID 23308107, 2013).
COVID-19 (19 papers, 2020 to 2025). A disease caused by infection with severe acute respiratory syndrome coronavirus 2. "Strikingly, TNFSF11 (TRANCE) and CXCL5 showed a strong negative correlation with most of the early-stage inflammatory markers indicating an opposite trend of these markers in COVID-19 pathogenesis." (PMID 33239683, 2020).
Paget disease (15 papers, 2011 to 2025). A malignant neoplasm composed of large cells with large nuclei, prominent nucleoli, and abundant pale cytoplasm (Paget cells). "SNPs located near TNFSF11, TNFRSF11A, and TNFRSF11B have been reported to be closely associated with Paget's disease, osteoporotic fractures, cardiovascular diseases, ankylosing spondylitis, and breast, and esophageal cancers." (PMID 34660648, 2021).
Autoimmunity (13 papers, 2012 to 2025). The occurrence of an immune reaction against the organism's own cells or tissues. "As noted, this locus is near the COG6 gene and the TNFSF11 gene, among others, which have been associated with autoimmunity." (PMID 41425598, 2025). "TNFSF11 (RANKL) was also found in FCRL4-expressing B cells in the context of autoimmunity, in the population defined as pro-inflammatory and probably contributing to RA pathogenesis." (PMID 40990023, 2025).
gastric cancer (11 papers, 2015 to 2024). A primary or metastatic malignant neoplasm involving the stomach. "The mutation rate of rs9533156 of TNFSF11 gene is higher in diabetic gastric cancer patients." (PMID 32655638, 2020). "In a further study on the relationship between TNFSF11 gene locus and clinical parameters of gastric cancer, we found that rs9533156 mutation may be related to the tumor size of gastric cancer." (PMID 32655638, 2020).
leukemia (10 papers, 2018 to 2026). A malignant (clonal) hematologic disorder, involving hematopoietic stem cells and characterized by the presence of primitive or atypical myeloid or lymphoid cells in the bone marrow and the blood. "To gain insight into the mechanism of osteoclast-mediated bone resorption, we evaluated mRNA expression of Rankl (Tnfsf11), M-CSF (Csf1), and Opg in leukemia cells." (PMID 29740160, 2018).
myocardial infarction (10 papers, 2012 to 2025). Gross necrosis of the myocardium, as a result of interruption of the blood supply to the area, as in coronary thrombosis. "Interestingly, TNFSF10, TNFSF11, and MCP-2 levels were lower in STEMI patients than in controls, which may reflect the complex regulatory mechanisms involved in inflammation and immune response following myocardial infarction." (PMID 39955425, 2025).
ameloblastoma (9 papers, 2018 to 2024). The most common odontogenic tumor, arising from the epithelial component of the embryonic tooth and usually affecting the molar-ramus region of the mandible or maxilla. "Ameloblastoma cells caused osteoblasts to increase their TNFSF11 (RANKL) expression." (PMID 34916549, 2021). "This study shows that TNFSF11 (RANKL) expression was significantly upregulated in ameloblastoma tumouroids and further supported by the RANKL ELISA results used to measure soluble RANKL in the culture supernatant." (PMID 36452176, 2022).
Crohn disease (9 papers, 2016 to 2025). A gastrointestinal disorder characterized by chronic inflammation involving all layers of the intestinal wall, noncaseating granulomas affecting the intestinal wall and regional lymph nodes, and transmural fibrosis. "TNFSF11 variants are associated with both heel bone mineral density and Crohn's disease in multiple studies." (PMID 33748968, 2021). "Based on a strong association between the gene TNFSF11 and Crohn’s disease, the authors inferred, and subsequently confirmed, that dishubzumab, originally developed for the treatment of osteoporosis, can be used against Crohn’s disease." (PMID 32543442, 2020). "The gene encoding RANKL, or TNFSF11, is positioned within a confirmed loci implicated in Crohn’s disease." (PMID 27631617, 2016). "Genome-wide association meta-analysis for Crohn’s disease (CD) identified a variant near the TNFSF11 gene that encodes RANKL and CD risk allele increased expression of RANKL in specific cell lines." (PMID 32670246, 2020).
gingivitis (9 papers, 2015 to 2026). A disorder involving inflammation of the gums; may affect surrounding and supporting structures of the teeth. "Following this upregulation in the early stage, Il6 and Tnfsf11 markedly increased in the PRT in IP, but Tnf and Il1b showed no apparent changes after the gingivitis phase." (PMID 38548743, 2024).
cervical cancer (8 papers, 2019 to 2023). A primary or metastatic malignant neoplasm involving the cervix. "RP11-384K6.2 is regulated by hsa-miR-657, which was found to have tumor-associated putative target genes that were associated with cervical cancer, including CDC14B, TNFSF11 and PTPN245." (PMID 33403041, 2021).
renal cell carcinoma (8 papers, 2014 to 2024). "CCL22, CRP, ICAM1, IFNG, PDGFRA, TGFB1 and TNFSF11 have been confirmed to be involved in the malignant progression and metastasis of renal cell carcinoma through different biological mechanisms." (PMID 34187413, 2021).
colorectal cancer (7 papers, 2014 to 2024). A primary or metastatic malignant neoplasm that affects the colon or rectum. "For example, TNFSF11 expression was positively associated with sensitivity to oxaliplatin, a common platinum-based antineoplastic drug for colorectal cancer, which is believed to function by blocking the duplication of DNA (r = 0.429, p < 0.001)." (PMID 34746134, 2021).
hyperparathyroidism (6 papers, 2010 to 2023). Hyperfunction of the parathyroid glands resulting in the overproduction of parathyroid hormone. "Production of RANKL, which is encoded by the Tnfsf11 gene, by osteocytes contributes to physiological bone resorption and some forms of pathological bone resorption, such as occurs during estrogen deficiency or hyperparathyroidism." (PMID 32870816, 2020).
lung adenocarcinoma (6 papers, 2017 to 2024). A carcinoma that arises from the lung and is characterized by the presence of malignant glandular epithelial cells. "Through these extensive analyses, we shed light on the potential role of TNFSF11 in lung adenocarcinoma, underscoring potential therapeutic targets for this malignancy." (PMID 38594779, 2024). "Our study may pave the way for innovative and precision medicine approaches in the treatment of lung adenocarcinoma (LUAD), based on differentiating levels of TNFSF11 expression." (PMID 38594779, 2024).
Camurati-Engelmann disease (4 papers, 2010 to 2023). Camurati-Englemann disease (CED) is a rare, clinically variable bone dysplasia syndrome characterized by hyperostosis of the long bones, skull, spine and pelvis, associated with severe pain in the extremities, a wide-based waddling gait, joint contractures, muscle weakness and easy fatigability. "Human disease associated with mutations in the RANKL gene is rare, although a novel mutation in the gene for transforming growth factor beta 1 (TGFβ1) and a missense change in TNFSF11 encoding RANKL may both contribute to the bone phenotype associated with Camurati-Engelmann disease." (PMID 24278766, 2013). "We report a 32-year-old man and his 59-year-old mother with a unique and extensive variant of Camurati-Engelmann disease (CED) featuring histopathological changes of osteomalacia and alterations within TGFβ1 and TNFSF11 encoding TGFβ1 and RANKL, respectively." (PMID 21541994, 2011).
allergic asthma (3 papers, 2021 to 2025). A asthma with a basis in a pathological type I hypersensitivity reaction. "Both subsets are highly proinflammatory and express various inflammatory cytokines and mediators such as Il4, Il5, Il13, Tnfsf11, Areg, Tgfb1, Calca and Furin, all of which are implicated in promoting allergic asthma and other allergic diseases." (PMID 40089475, 2025).
autoimmune hypothyroidism (3 papers, 2020 to 2024). "A common genetic etiology was proposed between hypothyroidism and OLP81 and our study supports this, indicating variation at nine loci (IFIH1, LPP, CEP43, TNRC18, C12orf42, TNFSF11, ST3GAL6, IL2RA, and IKZF3) that are strongly associated with both LP and autoimmune hypothyroidism." (PMID 38776927, 2024). "Five of the most significant hits after HLA—TNFSF11, CEP43, LPP, C12orf42, and IFIH1—and ten overall coincide with the same direction of effect as seen in the FinnGen and/or UKBB autoimmune hypothyroidism GWAS." (PMID 38776927, 2024).
membranous nephropathy (3 papers, 2012 to 2017). "In summary, our study identifies that miR-217 is a useful diagnostic biomarker and is involved in human podocyte cells apoptosis via targeting TNFSF11 in membranous nephropathy and provides a new diagnostic strategy for membranous nephropathy." (PMID 29214160, 2017). "miR-217 is a useful diagnostic biomarker and is involved in human podocyte cells apoptosis via targeting TNFSF11 in membranous nephropathy." (PMID 29214160, 2017).
age-related macular degeneration (2 papers, 2012 to 2025). Age-related loss of vision in the central portion of the retina (macula), secondary to retinal degeneration. "TNFSF11 is an inflammatory cytokine that correlates with age-related macular degeneration." (PMID 40869066, 2025).
autosomal recessive osteopetrosis (2 papers, 2014 to 2016). An autosomal recessive form of osteopetrosis caused by mutation(s) in at least 8 genes related to osteoclast function. "A study evaluating six individuals with autosomal recessive osteopetrosis secondary to mutations in TNFSF11, the gene encoding RANKL, did not identify significant differences from controls in the number of B and T-cell subsets, T-cell proliferation, or propensity to apoptosis." (PMID 24432249, 2014).
bronchiectasis (2 papers, 2020 to 2021). Segmental, irreversible dilation of the bronchial tree resulting in the accumulation of secretions which leads to obstruction. "A recent study identified different inflammation profiles when comparing gingival tissues of bronchiectasis patients having chronic periodontitis, with 7 genes significantly altered in bronchiectasis patients (LTA, LTB, TNFSF4, TNFSF11, TNFSF13, TNFSF13B, and TNFRSF11B)." (PMID 34765263, 2021).
myasthenia gravis (2 papers, 2020 to 2021). Myasthenia gravis (MG) is a rare, clinically heterogeneous, autoimmune disorder of the neuromuscular junction characterized by fatigable weakness of voluntary muscles. "Eight associations (five variants) were not previously reported to our knowledge, including associations near IRF1/IL5 for myasthenia gravis, near TNFSF11 for RF− JIA, and near CD2/CD28 for EGPA." (PMID 33239102, 2020). "In addition, single-nucleotide polymorphisms in either the TNFRSF11A locus (encoding RANK) or the TNFSF11 locus (encoding RANKL) are associated with the autoimmune syndromes myasthenia gravis and autoimmune vitiligo, respectively." (PMID 33075129, 2021).
nasal polyps (2 papers, 2023 to 2024). "A recent study found that Tnfsf11 was able to induce IL-5 and IL-13 in ILC2s via Tnfsf11a in chronic rhinosinusitis with nasal polyps." (PMID 37228603, 2023).
scrapie (2 papers, 2016 to 2021). A fatal disease of the nervous system in sheep and goats, characterized by pruritus, debility, and locomotor incoordination. "High-density qRT-PC studies investigating different times of the disease progression revealed overexpression of inflammatory genes Il1rn [IL-1Ra], Ccl8 [CCL8/MCP-2], Tnfsf11 [Tnfsf11/RANKL], and Osm [OSM]) at the preclinical stage in scrapie strain 22L-infected mice)." (PMID 33801117, 2021).
Diaphyseal sclerosis (1 paper, 2014). An elevation in bone density in one or more diaphyses. "TNFSF11 presents phenotypic similarities with CA2 for extramedullary hematopoiesis (HP:0001978), cranial nerve compression (HP:0001293), diaphyseal sclerosis (HP:0003034), hepatosplenomegaly (HP:0001433) and cranial hyperostosis (HP:0004437)." (PMID 25420641, 2014).
glaucoma (1 paper, 2023). Increased pressure in the eyeball due to obstruction of the outflow of aqueous humor. "TNFRSF11A is a target of diclofenac, an anti-inflammatory drug used to treat glaucoma, and TNFSF11 is a target of lenalidomide, denosumab, and anastrozole." (PMID 37893075, 2023).
hepatitis C (1 paper, 2021). "Therefore, TNFSF11 may be involved in these pathways and contribute to the hepatitis C chronic process." (PMID 34660648, 2021).
pancreatic cancer (1 paper, 2014). "Apart from this, growing evidence indicated that proinflammatory cytokines including interleukin-1 (IL-1), Il-6, IL-11, receptor activator of NF-κB ligand (RANKL, also known as TNFSF11), and TNFα play a pivotal role in pancreatic cancer initiation and progression." (PMID 24587996, 2014).
tumor (650 papers, 2003 to 2026). "The representative immunohistochemical staining results for normal and tumor tissues are provided, TNFSF11 is expressed in both normal tissues and tumor tissues, with localization on the cell membrane." (PMID 38594779, 2024). "The results indicated a significant overexpression of TNFSF11 in the PC-9 LV OE-TNFSF11 tumors, confirming the successful construction of the tumor model." (PMID 38594779, 2024). "GSE31210 dataset analysis also confirmed the elevated TNFSF11 expression in tumor tissues than the normal lung tissues (p<0.001)." (PMID 38594779, 2024). "TNFSF11 expression by the osteoblasts in the 3D bone stroma model was upregulated by 6.3-fold by the introduction of AM-1 tumour mass compared to the control (3D bone stroma model) (p = 0.05)." (PMID 34916549, 2021). "In our studies, we show that in tumour tissue, the expression of the RANKL gene (Tnfsf11) was increased by both calcitriol analogues but not by calcitriol." (PMID 31595196, 2019). "In this analysis, we identified subtype‐specific events for Epi‐LumB tumors involving either DNA copy number loss or CpG promoter methylation over DZIP1, TNFSF11, ZIC5, COL4A2, COL4A1 and PCDH8 indicating candidate tumor suppressor genes." (PMID 25468711, 2015). "Several extrinsic factors previously reported to be associated with the tumor microenvironment were identified, including GCSF, THBS1, S100A8/A9, CCL2, TNF and TNFSF11." (PMID 25593989, 2014). "We further examined the differential expression of TNFSF11 in normal and tumor tissues utilizing the TCGA-LUAD dataset and tissue microarray, and probed the associations between TNFSF11 expression and clinicopathological parameters within the TCGA-LUAD dataset." (PMID 38594779, 2024). "Moreover, we investigated the function of TNFSF11 through gene knockdown or overexpression approaches and explore its function in tumor cells." (PMID 38594779, 2024). "Additionally, we noted that the tumor volume in the TNFSF11-overexpressing mice was significantly larger than that in the OE-NC group." (PMID 38594779, 2024). "In addition, a pairwise comparison of 59 LUAD tissues with adjacent normal tissues confirmed the higher expression of TNFSF11 in the tumor tissues than the paired normal tissues (p<0.001)." (PMID 38594779, 2024). "Indeed, the gene TNFSF11 contributes to tumor metastasis acting through MEK/ERK, which in turn activates NFKB, resulting in the activation of ICAM1." (PMID 24489837, 2014). "Notably, the final tumor weight was substantially lower in the erastin-treated group than in the vehicle group, underscoring erastin’s potent inhibitory impact on the growth of TNFSF11-overexpressing tumors." (PMID 38594779, 2024). "The results showed that six genes (BOLA3-AS1, AC124067.4, AL161772.1, SALL4, PHYHIPL, and TNFSF11) were significantly associated with the COAD immune subtype (p < 0.05), indicating that these seven genes could modulate tumor immune functions at the genetic level." (PMID 34746134, 2021). "Further, in vitro experiments were performed to examine the relationship between TNFSF11 and peroxisome related genes within LUAD tumor cells." (PMID 38594779, 2024). "In this study, we investigated TNFSF11 expression in LUAD using public databases and a tumor tissue microarray." (PMID 38594779, 2024). "Ten datasets included the expression data of TNFSF11 and CCR6-CCL20 mRNAs, which mediate the anti-tumor effects of IL-17A." (PMID 36098359, 2022). "According to the ELISA experimental data, tumor cells were able to secrete VEGFA and TNFSF11 (RANKL)." (PMID 34367994, 2021). "TNFRSF11B binding with TNFSF11 suppresses the recruitment of macrophages to lymph nodes and the migration of T cells, which indicates that TNFRSF11B enhances tumor lymph node invasion." (PMID 34938284, 2021).